RN7SKP184 (RN7SK pseudogene 184)
Gene: Miscellaneous RNA gene on chromosome 20 (53,097,652 to 53,097,984, forward strand). Ensembl gene ENSG00000199218.
Homologues: Orthologues: chimpanzee 7SK (99% identical). Paralogues in human: 7SK (74% identical), RN7SKP203 (73% identical), RN7SKP133 (72% identical), RN7SKP217 (71% identical), RN7SKP146 (71% identical), RN7SKP9 (71% identical), RN7SKP124 (71% identical), RN7SKP162 (71% identical), RN7SKP249 (70% identical), RN7SKP44 (70% identical), RN7SKP79 (70% identical), RN7SKP180 (70% identical), and 284 more.